TLR3 (toll like receptor 3)
Diseases named in the same sentence as TLR3 in open-access papers (continued):
Sharing a sentence is not in itself a finding about the gene and the disease.
inflammatory myopathies (3 papers, 2011 to 2024). "It is also understood that inflammatory myopathies express TLR3 near areas of infiltrating mononuclear cells." (PMID 39555101, 2024). "Expression of TLR3 and of proteins that could serve as autoantigens is readily detected in biopsies from patients suffering from inflammatory myopathies and may contribute to the pathophysiology of autoimmune myositis." (PMID 24224022, 2013).
cardiac diseases (2 papers, 2017 to 2025). "Therefore, it is likely that fibroblasts significantly contribute to the increased expression of TLR1, TLR3, and TLR7 and their downstream signaling pathways we previously observed in the myocardium of patients with cardiac disease." (PMID 39828779, 2025).
CNS tumors (1 paper, 2007). "In the CNS and CNS tumors, recent studies have reported that both microglia and astrocytes express TLR3." (PMID 17295916, 2007).
hematological malignancies (1 paper, 2017). "Heightened co-expression and dysregulated signaling associated with Toll-like receptor 3 (TLR3) and Wnt5a is an integral component of solid tumors and hematological malignancies." (PMID 29371911, 2017).
TLR3 also shares sentences with these, for which no sentence is quoted: viral diseases (9 papers); Allergy (8); Cerebral ischemia (6); idiopathic pulmonary fibrosis (5); acute lung injury (3); glomerulonephritis (3); kidney injury (3); leprosy (3); multiple myeloma (3); acute pancreatitis (2); anthrax (2); benign prostatic hyperplasia (2); candidiasis (2); H1N1 influenza (2); mycoses (2); nephritis (2); polyposis (2); toxic epidermal necrolysis (2); tuberculosis (2); acute myocardial infarction (1); acute myocarditis (1); Addison’s disease (1); adenoma (1); adrenal autoimmunity (1); alveolitis (1); Anorexia (1); anxiety disorder (1); aortic valve disease (1); arboviral disease (1); astrocytoma (1).
A further 99 diseases each share a sentence with TLR3 in 1 paper.